UQCRQ (ubiquinol-cytochrome c reductase complex III subunit VII)
Description:
Component of the ubiquinol-cytochrome c oxidoreductase, a multisubunit transmembrane complex that is part of the mitochondrial electron transport chain which drives oxidative phosphorylation. The respiratory chain contains 3 multisubunit complexes succinate dehydrogenase (complex II, CII), ubiquinol-cytochrome c oxidoreductase (cytochrome b-c1 complex, complex III, CIII) and cytochrome c oxidase (complex IV, CIV), that cooperate to transfer electrons derived from NADH and succinate to molecular oxygen, creating an electrochemical gradient over the inner membrane that drives transmembrane transport and the ATP synthase. The cytochrome b-c1 complex catalyzes electron transfer from ubiquinol to cytochrome c, linking this redox reaction to translocation of protons across the mitochondrial inner membrane, with protons being carried across the membrane as hydrogens on the quinol. In the process called Q cycle, 2 protons are consumed from the matrix, 4 protons are released into the intermembrane space and 2 electrons are passed to cytochrome c.
Synonyms: QP-C; QCR8; UQCR7; MC3DN4; QPC
Tractability: Small molecule: a structure with a bound ligand is known. Antibody: UniProt predicts a signal peptide or a membrane-spanning region. PROTAC: ubiquitination databases record sites on it; its protein half-life has been measured.
Gene: Protein-coding gene on chromosome 5 (132,866,626 to 132,868,847, forward strand). Ensembl gene ENSG00000164405.
Subcellular location: Mitochondrion inner membrane
Subcellular location (Human Protein Atlas): Mitochondria
Pathways (Reactome):
Metabolism: Complex III assembly; Respiratory electron transport
Metabolism of proteins: Mitochondrial protein degradation
Gene Ontology:
Biological process: cellular respiration; mitochondrial electron transport, ubiquinol to cytochrome c; cerebellar Purkinje cell layer development; hippocampus development; hypothalamus development; midbrain development; pons development; pyramidal neuron development; subthalamus development; thalamus development
Cellular component: mitochondrial inner membrane; mitochondrion; respiratory chain complex III
Genetic constraint (gnomAD): Loss-of-function variants: 9 observed, 8.66 expected, observed/expected ratio (o/e) 1.04, 90% interval 0.62 to 1.73. That is too few expected variants to judge how well the gene tolerates losing a copy. Missense variants: 112 observed, 119.22 expected, observed/expected ratio (o/e) 0.94, 90% interval 0.81 to 1.1. Synonymous variants: 50 observed, 45.53 expected, observed/expected ratio (o/e) 1.1, 90% interval 0.87 to 1.39.
Gene-disease validity (ClinGen):
ClinGen rates the evidence that UQCRQ causes each of these diseases.
Leigh syndrome (autosomal recessive): Limited. A progressive neurological disease defined by specific neuropathological features associating brainstem and basal ganglia lesions.
mitochondrial disease (autosomal recessive): Limited.
Homologues: Orthologues: chimpanzee UQCRQ (100% identical), macaque UQCRQ (84% identical), rabbit UQCRQ (84% identical), pig UQCRQ (83% identical), dog UQCRQ (82% identical), rat Uqcrq (80% identical), mouse Uqcrq (79% identical), guinea pig UQCRQ (77% identical), tropical clawed frog uqcrq (60% identical), zebrafish uqcrq (54% identical), Drosophila melanogaster UQCR-Q (46% identical), Caenorhabditis elegans F45H10.2 (33% identical), and 1 more.
Diseases named in the same sentence as UQCRQ in open-access papers:
UQCRQ is named in the same sentence as 19 diseases in open-access papers, as found by Europe PMC text mining. Sharing a sentence is not in itself a finding about the gene and the disease. The quoted sentences say what the papers report.
Alzheimer disease (1 paper, 2020). A progressive, neurodegenerative disease characterized by loss of function and death of nerve cells in several areas of the brain leading to loss of cognitive function such as memory and language. "Among the proteins involved in the Alzheimer's disease and Parkinson's disease pathways, in addition to the fact that we already know that COX7B, COX6A2 and UQCRQ affect the function of mitochondria, downregulation of CASP9 is thought to lead to neurodegenerative diseases." (PMID 33247215, 2020).
breast carcinoma (1 paper, 2025). "UQCRQ, a subunit of the mitochondrial respiratory chain, plays a role in oxidative phosphorylation and has been linked to poor treatment response in breast cancer." (PMID 40618351, 2025).
cardiomyopathy (1 paper, 2025). A disease of the heart muscle or myocardium proper. "Interestingly, changes in FGF21-responsive genes such as OXCT1, the SUCL complex, PDHA1, OGDH, ACO2, IDH3B, and ETC components (MT-CO2, COQ9, UQCRQ, SDHB/D and NDUFB7) are linked to mitochondrial deficiency syndromes manifesting cardiomyopathy and encephalopathy." (PMID 40998786, 2025).
larynx squamous cell carcinoma (1 paper, 2022). "We observed a gene cluster, containing three genes (UQCRQ, NDUFA2, and NDUFS4) with different expression in various tumor stages of larynx squamous cell carcinoma, in modules related to tumor stage." (PMID 35715770, 2022).
Stroke (1 paper, 2024). Sudden impairment of blood flow to a part of the brain due to occlusion or rupture of an artery to the brain. "Core genes (UQCRQ, USMG5 [ATP5MD], COX6C, NDUFB3, ATP5L [ATP5MG], COX7C, NDUFA1, NDUFA4) were highly expressed in septic shock and stroke samples." (PMID 39655053, 2024).
tumor (3 papers, 2022 to 2024). "Other proteins of our founded subnetwork, including COX4I1, UQCRC2, ATP5J (ATP5PF), and ENSP00000400168 (ATP5MF-PTCD1), and UQCRQ also play a role in mitochondrial ATP synthesis; they are also involved in tumor initiation, growth, and metastasis." (PMID 38637790, 2024).
cancer (2 papers, 2019 to 2022). A tumor composed of atypical neoplastic, often pleomorphic cells that invade other tissues. "Transcripts of UQCR11 and UQCRQ, the down-regulation of which was verified in our study via RT-qPCR, were also described to be regulated in carcinoma." (PMID 30602369, 2019).
cardiovascular disease (1 paper, 2020). "In this pathway, upregulation of COX7B, COX17, and ATP6V1G3 as well as downregulation of COX6A2 and UQCRQ may lead to CKD complications with cardiovascular disease." (PMID 33247215, 2020).
UQCRQ also shares sentences with these, for which no sentence is quoted: infection (4 papers); COVID-19 (2); central nervous system disorder (1); Encephalopathy (1); endometrial carcinoma (1); endometriosis (1); epidermolysis bullosa simplex (1); Parkinson disease (1); preeclampsia (1); prostate carcinoma (1); squamous cell carcinoma (1).